FGF2 (fibroblast growth factor 2)
Diseases named in the same sentence as FGF2 in open-access papers (continued):
Sharing a sentence is not in itself a finding about the gene and the disease.
angina (2 papers, 2022 to 2025). "For example, treatment with FGF2 encapsulated into sustained-release heparin-alginate coated capsules during coronary bypass graft surgery resulted in improved myocardial perfusion and a near complete cessation of angina related symptoms." (PMID 35295649, 2022).
apical periodontitis (2 papers, 2020). "However, high-frequency wave irradiation was found to promote healing of periapical lesions on the host side through increased expression of fibroblast growth factor 2 and transforming growth factor-β1 and could therefore be useful as an adjuvant nonsurgical treatment for apical periodontitis." (PMID 32991601, 2020).
autism (2 papers, 2015 to 2022). Persistent deficits in social interaction and communication and interaction as well as a markedly restricted repertoire of activity and interest as well as repetitive patterns of behavior. "The serum levels of CNTF were found to be lower and the levels of FGF-2 and LIF were found to be higher in children with autism compared to age-matched healthy controls." (PMID 25769033, 2015). "Conversely, the levels of pro-BDNF, FGF-2, and LIF were found to be increased in autism sera compared to control (pro-BDNF, Student’s t-test, p = 0.0043; LIF, Student’s t-test, p = 0.0216; FGF-2, Student’s t-test, p = 0.0194)." (PMID 25769033, 2015).
benign prostatic hyperplasia (2 papers, 2016 to 2023). A non-cancerous nodular enlargement of the prostate gland. "In prostatic hyperplasia fibroblasts expressing AR, fibroblast growth factor-2 (FGF-2) and fibroblast growth factor-7 (FGF-7) were overexpressed." (PMID 36902608, 2023).
Blindness (2 papers, 2021 to 2025). Blindness is the condition of lacking visual perception defined as a profound reduction in visual perception. "Also, SNA mediated FGF2-dependent expression of FN involved in the endothelial-mesenchymal transition leading to retrocorneal membrane formation and blindness." (PMID 34571852, 2021).
brain glioma (2 papers, 2021 to 2024). A malignant glioma that involves the brain. "VEGF-A and FGF-2 tests provide 100% certainty in detecting people actually suffering from brain glioma, while in the case of ALL, VEGF-A enabled the detection of 92.2% of people with the disease." (PMID 38473833, 2024). "In the statistical analysis, statistically significant differences were observed between the concentrations of VEGF-A, VEGF-R2, and FGF-2 with respect to the entire sample population and increasing malignancy of brain glioma." (PMID 38473833, 2024). "Our team confirmed the existence of significant differences in the concentrations of pro-angiogenic cytokines, such as VEGF-A, VEGF-R2, and FGF-2, in brain glioma in relation to the stage of the disease and the control group." (PMID 38473833, 2024). "The present study has examined the influence of the degree of malignancy of brain glioma and patients’ habits and predisposition to the disease, based on family history of cancer and on the concentrations of the growth factors VEGF-A and FGF-2 and the VEGF-R2 receptor." (PMID 38473833, 2024). "The presented methods for determining the tested cytokines (VEGF-A, VEGF-R2, and FGF-2) could be used primarily to differentiate benign grades of brain glioma from malignant grades, while the VEGF-A method could be used for the diagnosis of ALL." (PMID 38473833, 2024). "The diagnostic usefulness of the methods for determining VEGF-A, VEGF-R2, and FGF-2 in brain glioma and VEGF-A and FGF-2 in ALL was verified by ROC analysis." (PMID 38473833, 2024). "The remaining proteins (VEGF-R2 and FGF-2) allow the detection of people without brain glioma in the sample population at levels of 58.3% and 85.4%, respectively." (PMID 38473833, 2024). "There was a statistically significant high negative correlation between FGF-2 and VEGF-A and a statistically significant moderate negative correlation between VEGF-A and VEGF-R2 in brain glioma." (PMID 38473833, 2024). "However, a person with a negative brain glioma test result based on VEGF-R2 tests can be 59.6% certain that they do not have the disease, and in the case of FGF-2 tests, they have 100% certainty." (PMID 38473833, 2024).
breast ductal adenocarcinoma (2 papers, 2015 to 2017). A breast carcinoma arising from the ducts. "Additionally, the GeparQuinto study reported interactions between VEGFA SNPs and hormone receptor status, while our study indicated associations between VEGFA SNPs and ductal carcinoma, and FGF2 SNPs and receptor status." (PMID 28045923, 2017).
Chlamydial infection (2 papers, 2007 to 2011). "FGF2 may play additional roles in the pathogenesis of chlamydial infection, by potentiating the inflammatory response, by inhibiting apoptosis, or by modulating gene expression." (PMID 21998584, 2011).
cholestasis (2 papers, 2023 to 2025). Impairment of the bile flow caused by obstruction within the liver, or outside the liver in the bile duct system. "Experimental models have indicated that hypoxia triggers periportal expression of factors such as VEGF and fibroblast growth factor-2 (FGF-2), affecting cholangiocytes and hepatocytes and potentially promoting structural changes linked to cholestasis and biliary dysfunction." (PMID 40277920, 2025).
chronic asthma (2 papers, 2022 to 2025). An asthma that is characterized by the development of persistent airway inflammation and recurrent attacks of breathlessness and wheezing, which vary in severity and frequency. "Overall, these key findings suggest that LRP1 may promote ASM proliferation in mice with OVA-induced chronic asthma by activating the FGF2/ERK signaling pathway." (PMID 40338656, 2025). "Moreover, we observed that FGF2 protein expression was significantly elevated in the tracheal tissues of mice with OVA-induced chronic asthma compared with control mice." (PMID 40338656, 2025). "In summary, our results indicated that LRP1 was upregulated in ASM cells of mice with OVA-induced chronic asthma and that this upregulated LRP1 promoted ASM cell proliferation by activating the FGF2/ERK signaling pathway." (PMID 40338656, 2025). "Moreover, FGF2 protein abundance was positively correlated with serum total and anti-HDM IgE levels in the HDM-induced chronic asthma model (R2 = 0.857 and 0.783, P = 0.0008 and 0.0043, respectively)." (PMID 35093168, 2022).
dengue (2 papers, 2016 to 2021). "Other studies have also observed downregulation of PDGF and FGF-2 in dengue patients, while FGF-2 was reported to be upregulated in chikungunya patients." (PMID 34215212, 2021). "IL-13 and MCP-3 downregulation was observed only in chikungunya patients, while conversely PDGF-AB/BB and FGF-2 downregulation was unique in dengue patients." (PMID 34215212, 2021). "By using multiplex immunoassay, we compared host cytokine profiles between acute CHIKV and DENV infections by analysing serum cytokine levels of IL-1α, IL-4, IL-5, IL-8, IL-13, RANTES, MCP-3, eotaxin, PDGF-AB/BB, and FGF-2 from the sera of acute chikungunya and dengue fever patients." (PMID 34215212, 2021). "A paired comparison of these 15 cytokines (irrespective of the treatment group) showed that 12 (eotaxin, FGF-2, IFN-γ, IL-10, IL-1Ra, IL-1α, IL-8, IP-10, MCP-1, MDC, TNF-α and sCD40L) were differentially expressed between baseline and acute phase of dengue illness." (PMID 27459266, 2016).
dermatomyositis (2 papers, 2014 to 2025). Dermatomyositis (DM) is a type of idiopathic inflammatory myopathy characterized by evocative skin lesions and symmetrical proximal muscle weakness. "In an MDA-5 amyopathic dermatomyositis–ILD patient, adding MMF (1.5 g/day) improved PF ratio and lowered FGF-2, CX3CL1, IL-1ra, IL-17A, IP-10 and MCP-1." (PMID 40650314, 2025).
diabetic macular edema (2 papers, 2011 to 2021). "The effectiveness of anti VEGF therapies in patients with diabetic macular edema remains disputable and suggests that other hypoxia-induced molecular factors may be involved such as PDGF, IGF-1, HGF, bFGF/FGF-2." (PMID 21408222, 2011).
endometrial adenocarcinoma (2 papers, 2010). "In our previous study we highlighted a role for the pro-angiogenic fibroblast growth factor-2, secreted from endometrial adenocarcinoma cells, in regulating endothelial network formation and proliferation." (PMID 20840749, 2010). "In vitro and animal xenograft studies have shown that secretion of epithelial FGF2 in endometrial adenocarcinoma xenografts can enhance tumour growth by enhancing blood vessel size and width." (PMID 20092633, 2010). "To determine if the effects of PGF2α-FP receptor interaction in endometrial adenocarcinoma cells on endothelial cell function were mediated by FGF2, we used conditioned medium (CM) from Ishikawa FPS cells treated with vehicle or 100 nM PGF2α for 24 hours." (PMID 20092633, 2010). "We have shown previously that PGF2α-FP receptor signalling in endometrial adenocarcinoma cells can upregulate several angiogenic factors including fibroblast growth factor-2 (FGF2)." (PMID 20092633, 2010). "We previously demonstrated elevated expression of the FP receptor, FGF2 and FGFR1 in endometrial adenocarcinoma." (PMID 20092633, 2010). "Using a neoplastic epithelial cell line stably expressing the FP receptor to the levels observed in endometrial adenocarcinoma (Ishikawa FPS cells), we ascertained a role for FGF2, produced by PGF2α-FP receptor signalling, on epithelial cell proliferation." (PMID 20092633, 2010). "In human endometrial adenocarcinomas VEGF-A and FGF2 expression and secretion are elevated and both VEGF-A and FGF2 can stimulate angiogenesis in xenografts in vivo." (PMID 20092633, 2010). "In the present study we have shown that conditioned medium from endometrial adenocarcinoma cells, which stably express the FP receptor to the levels observed in endometrial adenocarcinomas (FPS cells) and produce FGF2, promotes endothelial network formation (differentiation) and proliferation." (PMID 20092633, 2010). "Moreover, we have shown that elevated PGF2α-FP receptor signalling in endometrial adenocarcinoma leads to upregulation of tumorigenic genes such as PTGS2 and angiogenic genes such as FGF2 and VEGF which regulate vascular function in a paracrine manner." (PMID 20840749, 2010). "In addition, we found that FP receptor, FGF2 and FGFR1 co-localised within the vascular endothelial cells in endometrial adenocarcinomas suggesting that PGF2α may directly and indirectly regulate endothelial cell function." (PMID 20092633, 2010).
endophthalmitis (2 papers, 2018 to 2022). An infectious process affecting the internal structures of the eye. "Thus, blockage of FGF-2 has been proposed as a potential adjunct therapy to treat C. albicans infection, though further studies are warranted to investigate the role of FGF-2 in Candida endogenous endophthalmitis." (PMID 35913202, 2022). "There was additionally elevated expression of 4 Growth factors including FGF2 (p = 0.000), TGFα (p = 0.000), GCSF (p = 0.000), PDGFAB.BB (p = 0.000), in patients with endophthalmitis when compared to all controls as shown in." (PMID 30296277, 2018).
epithelial dysplasia (2 papers, 2015 to 2024). "Therefore, expression of FGF-2 and FGFR-2 may serve as an adjunct to histopathologic assessment of epithelial dysplasia for evaluating progression and malignant transformation in PMOLs." (PMID 26465941, 2015).
Huntington disease (2 papers, 2016 to 2020). Huntington disease (HD) is a rare neurodegenerative disorder of the central nervous system characterized by unwanted choreatic movements, behavioral and psychiatric disturbances and dementia. "We propose several possible scenarios for experimental studies initiated via the extra-cellular ligands TGFB1, FGF2 and TNF aiming at restoring the cellular homeostasis in Huntington's disease." (PMID 27924190, 2016).
Hypercholesterolemia (2 papers, 2018 to 2020). An increased concentration of cholesterol in the blood. "The present study demonstrated that hypercholesterolemia increased the release of inflammatory cytokine TNF-α and then promoted intraplaque angiogenesis by enhancing VEGF-A/VEGFR-2 and FGF-2/FGFR-1 expression." (PMID 30125282, 2018).
hypophysis (2 papers, 2008 to 2021). "Originally isolated from bovine hypophysis in the 1970s, FGF-2 is a protein with a molecular weight of 17,000 that acts to promote proliferation of fibroblasts." (PMID 18596969, 2008).
Infertility (2 papers, 2021 to 2023). "We evaluated the association of five polymorphic variants in VEFGA (rs699947), FLT1 (rs722503), KDR (rs2071559, rs1870377) and FGF2 (rs308395) genes with infertility and recurrent implantation failure among Polish women." (PMID 36901702, 2023). "There are suggestion that infertile women with RIF could benefit from the use of platelet-rich plasma (PRP) containing growth factors (PDGF, EGF, TGFβ, VEGF, HGF, FGF2)." (PMID 36901702, 2023).
invasive carcinoma (2 papers, 2022 to 2023). A carcinoma that is not confined to the epithelium, and has spread to the surrounding stroma. "TIMER2.0 was used to identify the correlation between EGFR and other gene expressions in breast-invasive carcinoma subtypes with purity adjustments such as FGF2, FGFBP1, TGFA, TGFBR3, and IGF1R in all BRCA patients." (PMID 36430763, 2022). "FGF2 and IGHA1 had significant (p < 0.05) downregulation in invasive carcinoma compared with normal breast tissues." (PMID 37445737, 2023).
lung diseases (2 papers, 2021). "Other studies dealing with lung diseases suggest that FGF2 may be associated with airway inflammation, bringing up the possibility of FGF2-targeted therapy." (PMID 34136479, 2021).
malignant salivary gland tumors (2 papers, 2010 to 2022). "In malignant salivary gland tumors, theoverexpression of FGF2 and FGFR-1 facilitates neoplastic progression." (PMID 20379686, 2010). "Salivahas significantly higher levels of fibroblast growth factor 2 (FGF2) and fibroblast growth factor receptor 1 (FGFR1) in patients withsalivary gland tumours, making it a possible biomarker for the early detection of salivary gland cancers." (PMID 37693919, 2022).
meningioma (2 papers, 2012 to 2022). A generally slow growing tumor attached to the dura mater. "We found that several growth factors including EGFL6, IGF1, FGF2, FGF7, FGF9, and FGF11 were overexpressed in fibroblastic meningioma, especially EGFL6 gene with extremely high expression in benign meningioma tissues." (PMID 23285163, 2012). "Expression of FGF2, FGF7, FGF9, and FGF11 was significantly increased 3.19-, 48.32-, 27.15-, and 3.34-fold respectively in fibroblastic meningiomas compared with arachnoidal tissue by qRT-PCR." (PMID 23285163, 2012).
middle ear cholesteatoma (2 papers, 2021). "In addition, none of the clinical studies described any cases of middle ear cholesteatoma after topical application of FGF2 or EGF." (PMID 34306094, 2021).
myeloid leukaemia (2 papers, 2017 to 2021). "Many of those genes inhibited by SID peptide treatment (CD44, TGFβR2, LEF1, TCF7L2, FGF2, FGF5, ID2, PIK3R3) are known as direct TGIF1 targets in myeloid leukemia or embryonic stem cells." (PMID 29179446, 2017).
neuroendocrine tumor (2 papers, 2014 to 2021). "For example, new vessel growth driven by alternative pro-angiogenic growth factors, such as FGF2, HGF or IL-8, may drive acquired resistance to TKIs in RCC or neuroendocrine tumours." (PMID 24482243, 2014).
optic neuropathies (2 papers, 2014 to 2022). "Experimental studies in various disease models addressed mechanisms of action and indicated modulation of neurotrophic factors (IGF-1, BDNF, CNTF, FGF-2, TNF-α) and immunomodulators (IL-10, IL-6, COX-2, NF-κB) by electrical stimulation of the eye in optic neuropathies." (PMID 35361287, 2022).
oral mucosal ulcer (2 papers, 2018 to 2020). "Nal-P-113 promoted the repair of oral mucosal ulcers by increasing the EGF and FGF-2 expression and decreasing that of TGF-β1 in HIOECs, accelerating their proliferation and cell cycle progression." (PMID 30298136, 2018). "In this study, we postulated that Nal-P-113 could shorten the healing time of oral mucosal ulcers by changing the expression of EGF, FGF-2, and TGF-β1 in human immortalized oral epithelial cells (HIOECs), which would accelerate the cell cycle and promote cell proliferation and migration." (PMID 30298136, 2018).
oral submucous fibrosis (2 papers, 2015 to 2024). "The present study was undertaken to analyze expression of FGF-2 and its receptors FGFR-2 and FGFR-3 in 72 PMOLs, 108 OSCC and 52 healthy controls, and their role in risk assessment for malignant transformation of Leukoplakia (LKP) and Oral submucous fibrosis (OSMF) to OSCC." (PMID 26465941, 2015).
Osteochondroma (2 papers, 2016 to 2023). A common, benign cartiliginous neoplasm arising from the metaphysis of bone. "Moreover, Judith et.al32 reported variation in expression of FGF2, FGFR2, FGFR3, PTHrP, and PTHrP‐R in osteochondroma samples from HME and non‐HME patient." (PMID 36162830, 2023).
osteomalacia (2 papers, 2012 to 2014). Disorder caused by an interruption of the mineralization of organic bone matrix leading to bone softening, bone pain, and weakness. "We further investigated the mechanisms underlying complete minerization in the β-globin-FGF2 animals but development of osteomalacia in the SFFV-FGF2 animals." (PMID 22629419, 2012). "A recent report shows that overexpression of nuclear high molecular weight FGF2 isoform increases FGF23/FGFR/KLOTHO signaling, causing phosphate wasting and osteomalacia." (PMID 22629419, 2012). "Our earlier study shows that transplantation of mouse Sca-1+ hematopoietic stem/progenitor cells that are engineered to express a modified FGF2 leads to considerable endosteal/trabecular bone formation, but it also induces adverse effects like hypocalemia and osteomalacia." (PMID 22629419, 2012). "FGF2 administration impairs bone mineralization and high-level serum FGF2 leads to osteomalacia." (PMID 22629419, 2012). "The second major unintended effect of high-level FGF2 is osteomalacia." (PMID 22629419, 2012). "To test our hypothesis, we provided evidence that in non-myeloablative transplantation, high-level FGF2 can induce substantial trabecular bone formation but also induce overt osteomalacia." (PMID 22629419, 2012).
otorrhea (2 papers, 2021 to 2023). "An alternative approach has been to administer FGF2 every other day and this has been found to reduce otorrhea while allowing FGF2 to exert a continual effect." (PMID 35002617, 2021).
pancreatic adenocarcinoma (2 papers, 2001 to 2013). "We have investigated the effects of FGF-1 and FGF-2 on the behaviour and adhesion properties of human pancreatic adenocarcinoma cell lines (BxPc3, T3M4 and HPAF) that were previously characterised for the expression of FGFRs." (PMID 11401320, 2001). "In pancreatic adenocarcinoma, FGF-1 and FGF2 have been shown to up-regulate E-cadherin expression." (PMID 23554977, 2013).
Papillary Thyroid Carcinoma (2 papers, 2017 to 2022). "FGF2 and CCND1 have been reported to play role in migration and invasion in papillary thyroid carcinoma." (PMID 35456223, 2022).
Peri-Implantitis (2 papers, 2022). An inflammatory process with loss of supporting bone in the tissues surrounding functioning DENTAL IMPLANTS. "Additionally, chemokines levels of IL-8, RANTES, and MCP-1, and growth factor levels of VEGF, PDGF-AB/BB, and FGF-2 were highly expressed in the PICF of peri-implantitis compared to healthy implants (p < 0.05)." (PMID 36233685, 2022).
proliferative vitreoretinopathy (2 papers, 2021 to 2024). Vitreoretinal membrane shrinkage or contraction secondary to the proliferation of primarily retinal pigment epithelial cells and glial cells, particularly fibrous astrocytes, followed by membrane formation. "FGF2 is a known driver of EMT that, among other factors, has been described to play a role in inducing EMT in RPE cells in proliferative vitreoretinopathy (PVR)." (PMID 39601967, 2024).